BRCA2 (BRCA2 DNA repair associated)
Diseases named in the same sentence as BRCA2 in open-access papers (continued):
Sharing a sentence is not in itself a finding about the gene and the disease.
ovarian carcinoma (continued). "In contrast, breast epithelial tissue from women with germline mutations in the BRCA1 or BRCA2 genes exhibits DNA repair defects, leading to an elevated risk of breast and ovarian cancer, as well as premature aging." (PMID 41294748, 2025). "The “high-penetrance” genes BRCA1 and BRCA2 were identified by linkage studies in the 1990’s; protein truncating variants in these genes confer a substantial lifetime risk of epithelial ovarian cancer as well as breast cancer and other cancers." (PMID 39939714, 2025). "Genetic screening of mainly patients with breast and ovarian cancer has identified numerous BRCA1/BRCA2 variants of uncertain significance (VUS) that remain unclassified owing to a lack of pedigrees and functional data." (PMID 40232841, 2025). "Population studies of mutations in high-penetrance genes, such as BRCA1 and BRCA2, are crucial due to their strong association with breast and ovarian cancer." (PMID 40071159, 2025). "For example, germline PSVs in the BRCA1 and BRCA2 genes are associated with a significantly increased risk of breast and ovarian cancers in women, and breast and prostate cancers in men." (PMID 40779059, 2025). "For instance, BRCA1 and BRCA2 mutations impair HR, increasing susceptibility to DNA damaging drugs in breast and ovarian cancers." (PMID 40422251, 2025). "A role for BRCA2 splice variants in BRCA2 wild-type ovarian cancer has been suggested by a recent study investigating the effect of the splicing factor small nuclear ribonucleoprotein B (SNRPB)." (PMID 40724944, 2025). "Therapeutic benefits of PARPis have been observed in patients with cancer carrying germline mutations in the BRCA1 and BRCA2 genes, particularly for ovarian cancer cases." (PMID 41223417, 2025). "A significant portion of probands with breast/ovarian cancer from the Jewish community of Rome harbored the heterozygous BRCA2 c.7007G>C pathogenic variant." (PMID 40563557, 2025). "A systematic review examined the impact of dietary habits, weight changes, and physical activity on the risk of breast and ovarian cancer in women with P/LP variants in BRCA1/BRCA2 P/LP." (PMID 39858629, 2025). "Germline mutations in the BRCA1 and BRCA2 genes, which are ovarian cancer susceptibility genes, are common causes of HRRD." (PMID 41223417, 2025). "For instance, studies reveal that BRCA2 mutation predisposes women to hereditary breast and ovarian cancer." (PMID 41541272, 2025). "Risk-reducing salpingo-oophorectomy (RRSO) can substantially reduce ovarian cancer incidence in women carrying pathogenic BRCA1 or BRCA2 variants, which cause hereditary breast and ovarian cancer syndrome." (PMID 40862027, 2025). "We identified membrane, humbly, and extracellular matrix-associated genes specifically deregulated in BRCA1- and BRCA2-mutated breast and ovarian cancers through genomic mapping of public datasets." (PMID 40647506, 2025). "These BRCA1/BRCA2 mutations, linked to hereditary breast and ovarian cancers, lead to a distinct cancer phenotype." (PMID 40864792, 2025). "For instance, breast epithelial cells in women with genetic defects in breast cancer type 1 (BRCA1) or BRCA2 genes exhibit reduced DNA repair capacity, resulting in an increased risk of breast and ovarian cancer, as well as accelerated aging." (PMID 41294748, 2025). "Specifically, there are two genes, BRCA1 and BRCA2, and mutations in these genes increase the risk of developing breast and ovarian cancer." (PMID 40070605, 2025). "For example, mutations in the BRCA1 and BRCA2 genes greatly elevate the risk of developing ovarian cancer." (PMID 41333220, 2025). "Germline mutations in BRCA1 and BRCA2 significantly increase the susceptibility to both breast and ovarian cancer, as well as other cancers including pancreatic and prostate cancers." (PMID 41142596, 2025). "BRCA1 and BRCA2 tumor suppressor genes are primarily linked with hereditary breast and ovarian cancers and with other malignancies to a lesser extent." (PMID 40162152, 2025).
ovarian carcinoma (continued). "Regarding cancer type and gender in pathogenic variants, BRCA1 was more commonly associated with breast and ovarian cancer, while BRCA2 was more widely detected in prostate cancer, pancreatic cancer, cholangiocarcinoma, and others." (PMID 40249378, 2025). "Numerous studies revealed that BRCA2 mutation, which has been closely associated with breast and ovarian cancers, was linked to poor prognosis in patients with prostate cancer." (PMID 40660132, 2025). "The risk of ovarian cancer in this group of patients varies from 27% to 44% in the BRCA2-mutated and BRCA1-mutated patients, respectively." (PMID 38275400, 2024). "Germline BRCA1 or BRCA2 mutations yield ovarian cancer, most often HGSOC, with a lifetime unmitigated risk of 30–70%." (PMID 38352443, 2024). "We report in this study that loss of function in BRCA1 or BRCA2 results in distinct responses to Wnt signaling in ovarian cancer cells." (PMID 39028933, 2024). "Approximately 14–24% of individuals diagnosed with ovarian cancer harbor BRCA1/BRCA2 mutation and are often hereditary." (PMID 38796525, 2024). "Women carrying BRCA1 and BRCA2 pathogenic variants have a significant lifetime risk of breast and ovarian cancers, with rates of up to 85% and 65%, respectively." (PMID 39061189, 2024). "Our investigation revealed the most common mutations in the BRCA1 and BRCA2 genes associated with breast and ovarian cancer." (PMID 38785549, 2024). "Variants within these regions appear to trigger nonsense-mediated decay (NMD), resulting in the loss of BRCA2 expression and a markedly elevated susceptibility of ovarian cancer." (PMID 38397209, 2024). "In the pre-clinical setting, use of ATR/CHK1 inhibitors in combination with olaparib overcame olaparib-resistant in BRCA2-mutated ovarian cancer cell lines." (PMID 39135999, 2024). "In case 514 the maternal family history was positive for breast and ovarian cancer, however the BRCA2 variant was confirmed to be inherited from the father (small family with few female relatives)." (PMID 38415346, 2024). "A sequencing study revealed the presence of BRCA1/BRCA2 reversion mutations in cfDNA in 21 % of ovarian cancer patients who were resistant to therapy." (PMID 39492906, 2024). "Patients at a high risk from familial breast and ovarian cancer typically inherit one mutant and one normal (‘wild-type’) copy of BRCA2." (PMID 39711301, 2024). "To further confirm that HMGA1 promotes DNA repair via the NHEJ pathway, we knocked down BRCA1 and BRCA2 in TYK‐nu ovarian cancer cells to simulate a homologous recombination deficiency (HRD) state." (PMID 39690136, 2024). "Carriers of BRCA1 and BRCA2 mutations, who are unable to perform effective homologous recombination repair, face significantly increased risks of breast and ovarian cancers." (PMID 39456709, 2024). "A total of 190 BRCA1 mutations and 169 BRCA2 mutations were detected in the enrolled ovarian cancer population." (PMID 38817903, 2024). "Previous studies in ovarian cancer have shown that mutations in both genes are associated with a similar response to platinum-based chemotherapy, and BRCA2 mutations are also associated with an increased response rate to primary platinum-based chemotherapy." (PMID 39364320, 2024). "On the other hand, carriers of BRCA2 PGVs display: (i) an absolute risk of BC higher than 60%; (ii) an absolute risk of male BC ranging from 1.8 to 7.1%; and (iii) an absolute risk of epithelial ovarian cancer ranging from 13 to 29%." (PMID 38672070, 2024). "Germline BRCA1 or BRCA2 mutations yield ovarian cancer, most often HGSOC, with a lifetime unmitigated risk of 30% to 70%." (PMID 39225558, 2024). "Using an FTE cell line to model BRCA2 deficiency in ovarian cancer precursor cells, we show that the dormant origin firing occurring near TTSs leads to the accumulation of TTS-oriented HO-TRC events." (PMID 38830843, 2024). "Individuals with pathogenic variants of BRCA1 and BRCA2 are at higher risk of breast and ovarian cancers." (PMID 39507757, 2024).
ovarian carcinoma (continued). "Inherited mutations in MMR represent the second most common cause of hereditary ovarian cancer, after BRCA1/BRCA2 mutations, and underlies the Lynch syndrome that predisposes to colorectal, endometrial, and ovarian cancers." (PMID 39492835, 2024). "All the investigations clearly show that, not only for breast cancer, BRCA1 and BRCA2 mutations stand out as the foremost high-penetrance genetic risk factors for ovarian cancer." (PMID 38391958, 2024). "Jolie’s announcement drew widespread attention to the BRCA1 and BRCA2 gene mutations, which greatly elevate the risk of breast and ovarian cancer." (PMID 39767657, 2024). "Here, we report a BRCA2 splice acceptor variant, c.517-2A>G, found in breast and ovarian cancer families from Shetland." (PMID 39438716, 2024). "RRSO confers an associated ovarian cancer risk reduction of 80–90% and a breast cancer risk reduction estimated at 50%, particularly in BRCA2 carriers." (PMID 37864742, 2024). "Remarkably, the loss of BRCA2 function renders ovarian cancer cells with a more stable β-catenin, and these cells respond to Wnt treatment by preferential upregulation of the negative regulator Axin2." (PMID 39028933, 2024). "Most hereditary ovarian cancer cases are attributed to germline mutations in the BRCA1 or BRCA2 genes." (PMID 39338246, 2024). "A reduction in ovarian cancer risk following the use of oral contraceptives has also been observed for carriers of pV in BRCA1 or BRCA2 genes in several studies." (PMID 39259360, 2024). "Germline pathogenic genetic variants in the BRCA1 and BRCA2 genes are the most frequent causes of familial breast and ovarian cancer." (PMID 40225940, 2024). "BRCA2 is a tumor suppressor best known for mutations associated with hereditary breast and ovarian cancer, but mutations are also associated with predisposition to other cancers including childhood leukemia and neuroblastoma." (PMID 39767807, 2024). "Although most studies indicate that BRCA2 mutations are associated with prolonged survival in invasive epithelial ovarian cancer, we presented a case of a patient with BRCA1 mutation and extended survival benefit." (PMID 39272683, 2024). "Its principal objective is to enhance research endeavors and methodologies for the classification of variants in BRCA1, BRCA2, and additional genes associated with breast and ovarian cancer susceptibility." (PMID 38397209, 2024). "Hereditary BRCA1 or BRCA2 germline mutations have been identified in 5% to 10% of epithelial ovarian cancers, although tumor development in these individuals requires somatic inactivation of the remaining wild-type (WT) allele." (PMID 39028933, 2024). "The frequency of BRCA2 c.8187G > T was specifically higher in Asian population than other mutated sites and moderately higher in Chinese ovarian cancer patients than healthy people." (PMID 38509102, 2024). "Compared with the general population, female carriers of BRCA1 and BRCA2 mutations exhibit an increased lifetime risk of developing breast and ovarian cancer by 59% and 16.5%, respectively." (PMID 39201170, 2024). "In our registry, patients with both breast and ovarian cancers were more likely to carry a BRCA1 mutation (24.7%) than a BRCA2 mutation (10.8%)." (PMID 39061189, 2024). "According to the ClinVar, the BRCA2 variant has been reported for patients with PC, BC, and ovarian cancer." (PMID 39398917, 2024). "Our objective is to identify molecular pathways that are differentially regulated upon the loss of BRCA1 and BRCA2 functions in ovarian cancer." (PMID 39028933, 2024). "Cancer-predisposing germline gene mutations, mostly in BRCA1 and BRCA2, are better linked to breast and ovarian cancers." (PMID 39061183, 2024). "Despite their common roles in DNA repair, several clinical distinctions have been observed between BRCA1 and BRCA2 mutation carriers in the context of ovarian cancer." (PMID 39028933, 2024).
ovarian carcinoma (continued). "For example, mutations in the BRCA1 and BRCA2 genes serve as important biomarkers for breast and ovarian cancers." (PMID 39767657, 2024). "The only two genes with more than 2% of patients having germline mutations were BRCA1 and BRCA2 in ovarian cancer (5.3% and 2.8% respectively)." (PMID 39277826, 2024). "For example, BRCA1 and BRCA2 mutations are associated with an increased risk of second primary breast or ovarian cancer." (PMID 38770671, 2024). "The observed regional and population disparities in the prevalence of deleterious germline mutations, particularly in BRCA2 and mismatch repair genes, emphasize the significance of regional genetic variations in ovarian cancer (OC) susceptibility." (PMID 38509102, 2024). "In this study, we sought to identify molecular pathways that are differentially regulated in the context of BRCA1 and BRCA2 mutations in ovarian cancer." (PMID 39028933, 2024). "BRCA1 and BRCA2 are the most studied ovarian cancer susceptibility genes, and are associated with hereditary breast and ovarian cancer syndrome." (PMID 38509102, 2024). "For example, poly(ADP-ribose) polymerase (PARP) inhibitors in breast cancer gene 1 (BRCA1) or BRCA2 mutated ovarian cancers exploit this cancer intrinsic vulnerability and lead to synthetic lethal interactions with clinical relevance." (PMID 38475864, 2024). "We present the case of a 75-year-old female with simultaneous EGFR-mutated stage IV lung cancer and advanced BRCA2-mutated ovarian cancer, treated with a unique regimen." (PMID 38275832, 2024). "BRCA1 and BRCA2 mutations are responsible for a higher incidence of breast and ovarian cancer (from 55% up to 70% vs. 12% in the general population)." (PMID 38792636, 2024). "The SOLO2 trial evaluated olaparib maintenance therapy in patients with platinum-sensitive BRCA1 or BRCA2 mutations and relapsed ovarian cancer." (PMID 39590126, 2024). "Mutations in the BRCA1 and BRCA2 genes are known and significant risk factors for breast and ovarian cancer." (PMID 39728052, 2024). "Their mother was the carrier of BRCA2 c.7579delG variant and was eventually diagnosed with ovarian cancer, further indicating a role of this specific BRCA2 variant in ovarian disease pathogenesis." (PMID 39359934, 2024). "The association of BRCA1 and BRCA2 mutations with increased risk for developing epithelial ovarian cancer is well established." (PMID 39028933, 2024). "After recognizing the role that BRCA1 and BRCA2 genes have in susceptibility and prognostic evaluation in breast and ovarian cancer, several works have studied the association between aberrations of DNA-repair system genes and prostate cancer." (PMID 39335746, 2024). "Carriers of BRCA1 and BRCA2 pathogenic variants have lifetime risks of ovarian cancer and fallopian tube cancer of 40–60% and 15–30%, respectively." (PMID 38256099, 2024). "For example, women who have inherited BRCA1 mutations have a lifetime risk of developing ovarian cancer ranging from 40% to 60%, while those with BRCA2 mutations have a lifetime risk of 11% to 27%." (PMID 38817903, 2024). "The NHS Grampian clinical genetics team initially observed the BRCA2 splice acceptor variant, NM_000059.4(BRCA2): c.517-2A>G, in breast and ovarian cancer cases from Shetland." (PMID 39438716, 2024). "BRCA1 mutation patients are more common in C3, while BRCA2 mutation patients are mostly ovarian cancer C2-subtype, each having different prognoses." (PMID 38543119, 2024). "The objective of this study was to identify and classify the spectrum of mutations found in the BRCA1 and BRCA2 genes associated with breast and ovarian cancer in female patients in Romania." (PMID 38785549, 2024). "Individuals inheriting deleterious variants in either BRCA1 or BRCA2 exhibit elevated susceptibilities to various malignancies, notably breast and ovarian cancers, along with other malignancies." (PMID 38809921, 2024).
ovarian carcinoma (continued). "The mechanisms by which replication stress contributes to genomic instability in early BRCA2-mutated ovarian cancers are not well understood." (PMID 38830843, 2024). "PARPi have demonstrated excellent potential in clinical settings, especially when administered to patients with BRCA1 and BRCA2-associated breast and ovarian cancer." (PMID 38993666, 2024). "A well-established clinical example in this regard is the use of PARP inhibitors in BRCA1 or BRCA2 mutated ovarian cancers." (PMID 38475864, 2024). "For example, BRCA2 mutations are generally associated with lower HRD scores in prostate versus ovarian carcinomas." (PMID 38612902, 2024). "Women with a PV in BRCA1 and BRCA2 have a lifetime risk of 35–45% and 10–20% for ovarian cancer, respectively." (PMID 38907139, 2024). "The collected information highlights the significant role of BRCA1 and BRCA2 mutations in families with a history of two or more cases of ovarian cancer." (PMID 38391958, 2024). "Individuals with a germline mutation in BRCA1 exhibit a chance of 48.3% for ovarian cancer by 70 years old (95% confidence interval [CI] = 38.8–57.9%) and of 20% (95% CI = 13.3–29.0%) when the mutation is in BRCA2." (PMID 38641594, 2024). "The percentage of respondents associating BRCA1 and BRCA2 mutations with breast and ovarian cancer increased with age group (3.23–6.98–9.09%, p < 0.0108)." (PMID 39728052, 2024). "Our investigation indicates the most common mutations in the BRCA1 and BRCA2 genes, associated with breast and ovarian cancer in the Romanian population." (PMID 38785549, 2024). "For example, mutation in BRCA1 or BRCA2 tumor suppressor genes predispose individuals at risk for developing ovarian cancer and breast cancer." (PMID 38796525, 2024). "Mutations in the BRCA1 and BRCA2 genes significantly increase the risk of breast and ovarian cancers, with ovarian cancer typically associated with a poor prognosis." (PMID 39272660, 2024). "Additional research is required to investigate and confirm the significance of BRCA1/BRCA2 reversion mutations in ovarian cancer." (PMID 39492906, 2024). "Performing a salpingo-oophorectomy as a preventive measure in women with BRCA1 or BRCA2 gene mutations has a substantial effect by drastically reducing the risk of ovarian carcinoma and significantly lowering the overall mortality." (PMID 39338246, 2024). "Women with mutations in the human BRCA2 gene (hBRCA2) have an increased risk of developing breast and ovarian cancer throughout their lifetime.hBRCA2 transcribes proteins necessary for gene repair through homologous recombination (HR)." (PMID 39170587, 2024). "For example, sequencing the BRCA1 and BRCA2 genes can screen high-risk groups for hereditary breast and ovarian cancer, enabling early diagnosis and prevention." (PMID 39872399, 2024). "Women with inherited mutations in BRCA1 or BRCA2 face an elevated risk of developing breast and ovarian cancers." (PMID 39742378, 2024). "Studies have indicated that females with mutations in the BRCA1 gene face a 3 to 4 times higher risk of developing ovarian cancer compared to those with mutations in the BRCA2 gene." (PMID 38461424, 2024). "This study also demonstrated that patients with two inherited pathogenic mutations were more likely to develop ovarian cancer than those carrying a BRCA2 pathogenic variant alone." (PMID 39061189, 2024). "Genetic factors play a significant role; in particular, 72% of BRCA1 and 69% of BRCA2 mutation carriers have a higher risk of developing breast or ovarian cancers by the age of 80 years." (PMID 38543119, 2024). "One of the underlying characteristics of Fanconi anaemia is a predisposition to cancer due to increased levels of genomic instability, and BRCA1 and BRCA2 mutations are known to predispose individuals to breast and ovarian cancers." (PMID 38711848, 2024).